HTR7 (5-hydroxytryptamine receptor 7)
Diseases named in the same sentence as HTR7 in open-access papers (continued):
Sharing a sentence is not in itself a finding about the gene and the disease.
Stroke (1 paper, 2025). Sudden impairment of blood flow to a part of the brain due to occlusion or rupture of an artery to the brain. "Eight common genes were found across all three compounds and stroke: MAPK1, PRKCB, PRKCG, HDAC1, HTR1A, HTR2A, HTR2C, and HTR7." (PMID 41011194, 2025).
tauopathy (1 paper, 2024). Neurodegenerative disorders involving deposition of abnormal tau protein isoforms (tau proteins) in neurons and glial cells in the brain. "In these animals we examined short-term memory and the expression of genes involved in the development of tauopathy (Htr7 and Cdk5), as well as biomarkers of neurodegenerative processes – the Bdnf gene and its receptors TrkB (the Ntrk2 gene) and p75NTR (the Ngfr gene)." (PMID 39027123, 2024).
thyroid cancer (1 paper, 2022). "Several hypermethylated genes (GALNTL6, HTR7, SPOCD1, CDH16 and GRM5) related to thyroid cancer have been discovered to be up-regulated in our study, as were investigated in other reports to mentioned in the following text." (PMID 35267472, 2022).
triple-negative breast carcinoma (1 paper, 2025). An invasive breast carcinoma which is negative for expression of estrogen receptor (ER), progesterone receptor (PR), and human epidermal growth factor receptor 2 (HER2). "Dandan Zhan’s study demonstrated that HTR7 expression was inhibited in invasive mixed breast carcinoma, whereas Venhar Cınar’s study revealed that HTR7 expression was increased in triple-negative breast cancer (TNBC)." (PMID 41237175, 2025).
cancer (9 papers, 2009 to 2025). A tumor composed of atypical neoplastic, often pleomorphic cells that invade other tissues. "Our study suggests that HTR7 has a specific diagnostic value in 18 cancers, especially in COAD, HNSC, KIRC, PCPG, and READ." (PMID 41237175, 2025). "Analyzing specific cancers, HTR7 methylation was associated with more immune cell infiltration in COAD, OV, KIRP, ACC, THCA, READ, UVM, and GBM." (PMID 41237175, 2025). "Considering the critical role of immune infiltration in oncology progression, we explored the association of HTR7 expression with immune cell infiltration and immune checkpoints in pan-cancer." (PMID 41237175, 2025). "To explore HTR7 gene variants in pan-cancer, we utilised the cBioPortal platform, which revealed that the frequency of HTR7 gene variants was highest in UCEC and SKCM (>4%)." (PMID 41237175, 2025). "The differential expression of HTR7 in tumor tissues has prompted investigations into its diagnostic value for cancers." (PMID 41237175, 2025). "To study the association between HTR7 expression level and prognosis, we performed a survival association analysis for each cancer, including OS, DSS, PFI, and DFI." (PMID 41237175, 2025). "Our study suggested that HTR7 may have both pro-cancer and anti-carcinogenic effects, with specific diagnostic values and the ability to predict cancer prognosis." (PMID 41237175, 2025). "HTR7 has a specific diagnostic value in 18 cancers, especially in COAD, HNSC, KIRC, PCPG, and READ." (PMID 41237175, 2025). "HTR7, the gene encoding the 5-HT7 receptor, a G protein-coupled receptor, has been shown in several studies to be associated with cancer development." (PMID 41237175, 2025). "Regarding individual cancers, in PRAD, HTR7 was associated with the infiltration of 27 immune cells." (PMID 41237175, 2025). "To more comprehensively analyze the influence of HTR7 on cancers, we explored the genes related to HTR7 and performed GO and KEGG enrichment analyses." (PMID 41237175, 2025). "In the analysis of TME, our findings showed that in most cancers, HTR7 expression was positively correlated with infiltration of monocytes, macrophages, and myeloid dendritic cells and negatively correlated with Th1 infiltration." (PMID 41237175, 2025). "We used several public databases to perform a comprehensive pan-cancer analysis to determine the potential role of HTR7 in diagnosing tumors, predicting prognosis, and predicting cancer immunotherapy response." (PMID 41237175, 2025). "We explored the impact of HTR7 expression on the activity of several well-known cancer pathways." (PMID 41237175, 2025). "We comprehensively explored the correlation between HTR7 and 33 cancers, including gene expression, diagnostic value, prognosis, clinical and pathological staging, TME, DNA methylation, cancer pathways, and drug sensitivity, using databases including TCGA, GTEx, UALCAN, HPA, and cBioportal." (PMID 41237175, 2025). "In 21 cancers, HTR7 and Th1 infiltration were negatively correlated." (PMID 41237175, 2025). "According to our knowledge, this study is the first to illustrate the dual oncogenic and tumor-suppressive potential of HTR7 across many cancer types, particularly uncovering previously unreported high expression in malignancies like KIRC, KIRP, PAAD, PCPG, and UCS." (PMID 41237175, 2025). "To explore the expression level of HTR7 in pan-cancer, we used the TIMER and TCGA + GTEx databases." (PMID 41237175, 2025). "We first explored the promoter methylation level of HTR7 in cancers." (PMID 41237175, 2025). "It is noteworthy that HTR7 was lowly expressed in all of these tumors, which once again suggests that HTR7 may play a cancer-suppressive role in these tumors." (PMID 41237175, 2025). "Therapies targeting HTR7 are being investigated in several cancers." (PMID 41237175, 2025). "Our research revealed that HTR1D, HTR2B, and HTR7 were highly expressed in pan-cancer." (PMID 39766808, 2024).
cancer (continued). "However, clinical and basic studies on the cancer pathway of HTR7 in most tumors are still scarce, and our results may inform further studies in the future." (PMID 41237175, 2025). "Our findings significantly enhance the understanding of HTR7’s role in cancer; nonetheless, further mechanistic investigations are necessary to reveal fundamentally unique pathways that may explain the dual functionality of HTR7 in cancer." (PMID 41237175, 2025). "Therefore, our study systematically analyzed the association of HTR7 with transcript levels, diagnostic value, clinicopathologic features, survival prognosis, TME, DNA methylation, cancer pathways, and potential drugs in 33 cancers, hoping to inform future research targeting HTR7." (PMID 41237175, 2025). "Subsequently, we further analyzed whether the expression levels of HTR7 influence cancer prognosis." (PMID 41237175, 2025). "We found that the promoter methylation level of the HTR7 was increased in BRCA, COAD, PRAD, and STAD, corroborating the fact that HTR7 can play an oncogenic role in these cancers." (PMID 41237175, 2025). "Additionally, C5 and the high expression of HTR5A were tightly related, indicating that HTR5A may have a cancer-suppressing function, and HTR7’s high expression was related to C2, which indicated that HTR7 related to a high level of immune infiltration and intertumoral heterogeneity." (PMID 39766808, 2024). "The expression level of HTGPCRs in different tumors showed the specificity of genes and tumors, for example, HTR1B and HTR2B were lowly expressed in most cancers while HTR1D and HTR7 were highly expressed in most cancers." (PMID 39766808, 2024). "There is a lack of comprehensive and in-depth pan-cancer analyses on HTR7, which is important for a full understanding of the role of HTR7 in cancers." (PMID 41237175, 2025). "In contrast, MCF7 and T47D, both of which are ER positive cancer cells, lacked any detectable HTR7 transcript." (PMID 19903352, 2009). "The data from the Cancer Therapeutics Response Portal (CTRP) showed that HTR7 expression was positively correlated with IC50 of several drugs, including chlorambucil, hydrochloride, insular, and vorinostat, implying that these drugs may be resistant to high HTR7 expression." (PMID 41237175, 2025). "In terms of clinical staging, we found that the expression of HTR7 in BLCA, BRCA, and SKCM was negatively correlated with the clinical staging, and HTR7 was also lowly expressed in these tumor tissues, which further suggests that HTR7 may have a cancer-suppressive role in BLCA, BRCA, and SKCM." (PMID 41237175, 2025).
tumor (9 papers, 2009 to 2025). "Possibly, the phosphorylation of AKT by HTR7 is linked with the tumor progression." (PMID 40231252, 2025). "Existing studies suggest that targeting HTR7 has some potential in tumor therapy." (PMID 41237175, 2025). "Among these 5-HTRs, HTR7, HTR2A, HTR2B, and HTR2C were extensively studied in different tumor tissues." (PMID 37795441, 2023). "This is possibly due to the tumor-promoting roles of other serotonin receptors, such as HTR1D 42 and HTR7 43, that are slightly upregulated in OC and can activate the SRC signaling." (PMID 34093864, 2021).
neurodegenerative disease (2 papers, 2023 to 2025). A disorder of the central nervous system characterized by gradual and progressive loss of neural tissue and neurologic function. "Therefore, based on the results of mRNA sequencing analysis, we further analyzed the effect of ADP‐hep on Htr7 signaling, and the results of KEGG‐human diseases showed that up‐regulated DEGs were significantly enriched in neurodegenerative diseases and AD." (PMID 40501108, 2025).
neurological diseases (2 papers, 2022 to 2024). "The alteration in mRNA levels of Htr2a, Htr4, Htr7, Htr5b, Htr6, and Htr3 indicate that serotonin may increase the risk of CJL mediated neurological disorders." (PMID 36582489, 2022). "The variations of HTR7 and MME have not been reported on the mechanism related to bortezomib, but have been verified to be associated with neurological diseases." (PMID 38686049, 2024).
inflammation (1 paper, 2025). Aberrant reaction of the microcirculation characterized by movement of fluid and leukocytes from the blood into extravascular tissues. "This suggested that HTR7 may be positively connected with IL-17-mediated neuroinflammation and the poor cognitive functioning resulting from brain inflammation." (PMID 39977438, 2025).
HTR7 also shares sentences with these, for which no sentence is quoted: epilepsy (3 papers); memory impairment (3); mood disorder (2); neuroblastoma (2); psychiatric disorder (2); Rett syndrome (2); Alzheimer disease (1); anxiety disorder (1); autism spectrum disorder (1); breast tumors (1); cerebral amyloid angiopathy (1); fragile X syndrome (1); frontotemporal dementia (1); gastrointestinal disorders (1); generalized anxiety disorder (1); hepatic disorders (1); hepatocellular carcinoma (1); hyperprolactinaemia (1); infarction (1); itch (1); Obesity (1); osteosarcoma (1); respiratory depression (1); sleep disorder (1); small-intestinal neuroendocrine neoplasms (1); stress-related disorder (1); temporal lobe epilepsy (1).